MMP2 (matrix metallopeptidase 2)
Diseases named in the same sentence as MMP2 in open-access papers (continued):
Sharing a sentence is not in itself a finding about the gene and the disease.
glioma (continued). "Moreover, the tumor subgroups in the patients from our collection and those from the TCGA GBM dataset with a higher MMP2 level also had shorter DFS and OS, indicating that the MMP2 level was a serviceable biomarker for prognosis‐based glioma subclassification." (PMID 29733521, 2018). "In comparison with nontumoral brain tissues, gliomas expressed more MMP2, the expression of which significantly increased with an increase in glioma grade." (PMID 29733521, 2018). "The activated complement system signaling may provide an alternative mechanism for the NF-κB mediated overexpression of MMP-2 and MMP-9 in glioma cells by means of C5a-C5aR." (PMID 30208949, 2018). "MMP2 degrades ECM components and facilitates glioma cell dispersal." (PMID 28670569, 2017). "MMP-2 and MMP-9 are negatively correlated with the prognosis of glioma patients." (PMID 28701209, 2017). "Thus, we conducted a meta-analysis to determine the correlation of MMP-2 and TIMP-2 expressions with the prognosis of patients with gliomas." (PMID 26729052, 2017). "As regulators of cell adhesion and invasion, MMP2 and MMP9 are closely involved in augmentation of the invasive capability of glioma cells and correlate with the degree of histologic malignancy and clinical outcome, whereas Ki67 indicates the proliferative ability of the tumor." (PMID 28287612, 2017). "MMP-2 is specifically upregulated in gliomas and related cancers, but is not normally expressed in the brain." (PMID 30873475, 2017). "In gliomas, c-MET and MMP-2 may share several properties promoting tumor survival, angiogenesis, and invasion, and in fact similar to MMP-2, cells with strong c-MET expression were found in blood vessels and perinecrotic areas." (PMID 28234925, 2017). "MMP-2 and TIMP-2 expressions in the tissues of gliomas were only investigated by IHC method." (PMID 26729052, 2017). "Glioma-derived versican interacts with TLR2, inducing CNS microglia and macrophages to express membrane type 1-matrix metalloproteinase 1 (MT1-MMP) that activates MMP2." (PMID 29410971, 2017). "Taken together, these results illustrate that SH3GL2 may play an important role in inhibiting glioma cell migration and invasion by suppressing STAT3/MMP2 signalling pathway." (PMID 28470949, 2017). "To further understand the role of APOBEC3G in Smad2 deactivation in gliomas, we determined its role in mediating the expression of the Smad2-targeted genes Thrombospondin 1 (TSP-1), matrix metallopeptidase 2 (MMP2) and TIMP metallopeptidase inhibitor 1 (TIMP-1)." (PMID 28903341, 2017). "In our study, we found that blocking the expression of RACK1 greatly inhibited migration and invasion ability of glioma cells, and discovered that knockdown of RACK1 significantly decreased the expression of EMT markers, such as MMP2 and MMP9, ZEB1, N-cadherin, and Integrin-β1." (PMID 27763568, 2016). "Although Ang2 expression has been previously associated with invasion in gliomas, this invasion has not previously been linked to TEM recruitment but rather to mechanisms such as the induction of MMP2 expression via integrins." (PMID 26910374, 2016). "We observed that the expression of apoptosis-related factors (cleaved caspase 3 and Bad) was lower, while the expression of anti-apoptosis (Bcl2), invasion (MMP2 and MMP9) and chemokine pathway related factors (CXCL10 and CXCR3) was higher in glioma tissues than in normal tissues." (PMID 26506595, 2016). "Judging from these results, we can suggest that the reduction of MMP2 expression levels, mediated by JNK inhibition, is sufficient and strong enough to alter the invasive behavior of the cell, impairing the infiltration of glioma." (PMID 25596741, 2015). "These include skin, decidual cells of the placenta, nucleus pulposus tissue of intervertebral disc, and MMP2 of glioma; however, it has not been documented on reduced MMP2 or MMP9 activity, reversed in response to the cytokines signal." (PMID 25774514, 2015).
glioma (continued). "In addition, EFEMP1 has been shown to be overexpressed concomitantly with MMP-2, MMP-9 and ADAMTS-5 in glioma." (PMID 25987128, 2015). "The matrix metalloprotease MMP-2 is expressed in glioma and other tumors but is not present in normal brain tissues." (PMID 25826056, 2015). "Increased levels of MMP-2 and 9 were observed in CSF of high-grade glioma patients, and a larger study confirmed increased plasma levels of MMP-9 and TIMP-1 in patients with both grade II and IV glioma compared to healthy controls." (PMID 25720744, 2015). "Protein analysis of tumors from animals fed the KD showed reduced expression of both pro- and activated-MMP-2, and the mesenchymal marker, vimentin, which is upregulated in the epithelial-to-mesenchymal transition (EMT) that occurs within invasive glioma cells." (PMID 26083629, 2015). "Here we showed that MMP2 expression and activity are increased in glioma cell lines that do not express WNK2." (PMID 25596741, 2015). "Incidentally, CLC 3 and MMP2 are both over and co-expressed specifically in gliomas rather than in the surrounding normal tissue." (PMID 26010603, 2015). "The PI3K/AKT signaling pathway regulates glioma cell proliferation and invasion, while pharmacological inhibitors of PI3K/Akt signaling (LY294002 and A443654) reduce the motility of GBM cells and diminish the level of MMP-2 activity and MMP-2 expression." (PMID 25202424, 2014). "MMP2 and MMP9 protein expression levels are key indicators of glioma cell invasion." (PMID 23251243, 2013). "Similar results were also found in glioma, SPARC up-regulated the expression of MMP-2 and MMP-9." (PMID 22879971, 2012). "In glioma cells, it was reported that CTX inhibits cell invasion by reducing MMP2 activity." (PMID 23304519, 2012). "In particular, MMP-2 and MMP-9 are the two most abundant MMPs found in gliomas." (PMID 20587068, 2010). "Therefore, it has been proposed that MMP-2 and MMP-9 inhibitors can act as potential drugs for the treatment of gliomas." (PMID 20587068, 2010). "In this study we determined whether or not doxycycline could block MMP-2 and MMP-9 activities, by measurements of doxycyline-mediated MMP-2 and MMP-9 inhibition in vitro using epidermal growth factor receptor (EGFR) transfected U251 glioma cell lines." (PMID 18186943, 2008). "To determine whether doxycycline can block MMP activity, we measured the extent of doxycyline-mediated MMP-2 and MMP-9 inhibition in vitro using epidermal growth factor receptor (EGFR) transfected U251 glioma cell lines." (PMID 18186943, 2008). "Doxycycline can block MMP-2 and MMP-9 activities from glioma cells in vitro." (PMID 18186943, 2008). "In addition, we investigated As2O3-mediated suppression of glioma cell invasion which likely involves PKC signaling, ERK phosphorylation, and MMP-2 activation." (PMID 18294404, 2008). "These experiments demonstrated that the berberine-As2O3-mediated enhanced suppression of ERK phosphorylation led to a decrease of the levels of ODC, MT1-MMP, and MMP-2 in C6 glioma cells to values that resembled those observed in negative controls." (PMID 18294404, 2008). "However, it is not entirely clear if proteolytic degradation of versican by MMP-2 and ADAMTS-1 and 4 induced by TGF-β2 has a pathophysiological role in glioma progression." (PMID 17453002, 2007). "In particular, MMP-2 and MMP-9 render critical for glioma cell invasion." (PMID 14647148, 2003). "Examination of MMP-2, MT1-MMP, a membrane-bound MMP which is thought to facilitate rapid processing of pro-MMP-2, and TIMP-2 showed that the expression patterns of MMP-2 and MT1-MMP were very similar among the examined glioma cell lines." (PMID 14647148, 2003).
glioma (continued). "Preclinical studies suggest that propofol may inhibit glioma cell proliferation, invasion, and migration and promote apoptosis through mechanisms such as the upregulation of microRNA-218 and suppression of HIF-1α and MMP-2 activity." (PMID 40870507, 2025). "Additionally, MMPs, including MMP-2 and MMP-14, facilitate the recruitment and migration of regulatory T-cells (Tregs) and myeloid-derived suppressor cells (MDSCs) into glioma tissue by remodeling extracellular matrix components and modulating chemokine gradients." (PMID 40265458, 2025). "Interestingly, the TME of gliomas modifies MMP-2 in a way that a naturally occurring peptide in the venom of scorpion species Leiurus quinquestriatus, chlorotoxin (CLTX), binds to MMP-2 on the surface of gliomas but not of normal brain tissue." (PMID 41561543, 2025). "The CCK-8 experiment indicated that upregulating miR-760 had a negative effect on the capacity of glioma cells to grow; conversely, this effect could be restored by the MMP2 overexpression plasmid on cell proliferation (p<0.01)." (PMID 38706905, 2024). "Additionally, CTX disrupts ClC-3 by interacting with a complex protein composed of matrix metalloproteinase-2 (MMP-2), membrane type 1 matrix metalloprotease (MT1-MMP), and the tissue inhibitor of matrix metalloproteinase-2 (TIMP-2) on the surface of glioma cell membranes." (PMID 39770577, 2024). "In addition, L1 overexpression significantly induces the upregulation of MMP2 and MMP9 expression in U87, T98, and GBM1 cells, suggesting that L1 might promote tumor invasion through upregulating MMP2 and MMP9 in glioma cells." (PMID 36708044, 2023). "In gliomas, it is reported that MMP-2 and CIC-3 form a protein complex located within the same membrane domain targeted by CTX and could potentially inhibit glioma cell invasion through the induction of MMP-2/ClC-3 protein complex endocytosis." (PMID 37444498, 2023). "According to Western blotting results, TUSC7 overexpression group had significantly lower expressions of MMP2, MMP3 and MMP9 than NC group, whereas they were obviously elevated after silencing TUSC7, suggesting that TUSC7 could inhibit the migration of glioma cells by degrading MMP2, MMP3 and MMP9." (PMID 37100464, 2023). "Similarly, MMP2 and MMP9 function as the key mediator of VM in glioma, while the suppression of Tenascin‐c attenuates AKT phosphorylation, and downregulates MMP2 and MMP9 expression, thus repressing VM in gliomas." (PMID 34890108, 2022). "However, TLR2 upregulated MMP2 and MMP9 expression in GL261 glioma cell lines and promoted tumor invasion, indicating that TLR2 signaling in GSCs is involved in the invasiveness of glioma." (PMID 36611945, 2022). "SCIN and MMP2/9 are negative prognostic factors resulting in worsening glioma patients’ survival." (PMID 36291348, 2022). "Some SynB3‐PVGLIG‐PTX is hydrolyzed by MMP‐2 in the extracellular matrix of glioma cells, and the released PTX plays an antitumor role in the tumor microenvironment, while other SynB3‐PVGLIG‐PTX molecules can also enter glioma cells and be hydrolyzed by MMP‐2 to release PTX." (PMID 33552853, 2021). "Moreover, MMP-2, MT1- and MT2-MMP have been localized in glioma cells." (PMID 34638718, 2021). "Interestingly, MMP2 is released as an inactive molecule and requires the presence of MT1-MMP on the surface of TAMs to be activated, indicating that TAMs and glioma cells can coordinate their functions in the TME." (PMID 34690699, 2021). "The authors suggest that since PER2 targets the Wnt/β-catenin signaling pathway in GSCs, the downregulation of critical proteins involved in the invasiveness and stemness of GSCs, such as Wnt7b, β-catenin, MMP2, MMP9, and c-Myc, may explain the tumor suppressive role of PER2 in gliomas." (PMID 34361055, 2021). "Therefore, the results indicated that PPFIBP1 might promote migration and invasion by stimulating expression of MMP-2 via activating of JNK and c-Jun in glioma cells." (PMID 34480020, 2021).
glioma (continued). "However, the mechanisms that regulate MMP-2 gene transcription in human glioma cells are not fully elucidated." (PMID 29285298, 2017). "Glioma-derived versican converts microglia into a pro-tumorigenic phenotype characterized by the upregulation of MMP9 and MMP14 (as observed here in response to LPA); in particular, MMP14 promotes activation of GBM-derived MMP2 that favors the invasive potential of malign glioblastoma cells." (PMID 29258556, 2017). "Therefore, we speculate that STAT3/MMP2 signalling may be involved in SH3GL2 mediated migration and invasion of glioma cells." (PMID 28470949, 2017). "In addition, TGFβ2 induces the expression of MMP2 in glioma cells and suppresses the expression of tissue inhibitor of metalloproteinases (TIMP)-2, which degrades the extracellular matrix and subsequently promotes glioma invasion." (PMID 29410971, 2017). "Furthermore, silenced ZFAS1 could impair migration and invasion by inhibiting the epithelial–mesenchymal transition through reducing the expression of MMP2, MMP9, N-cadherin, Integrin β1, ZEB1, Twist, and Snail as well as increasing E-cadherin level in glioma." (PMID 29245995, 2017). "Similarly, a number of studies investigated the impact of MMP-2 expression on the prognosis of patients with gliomas, but there were also no consistent results." (PMID 26729052, 2017). "Furthermore, recent studies demonstrated that vesicles produced by irradiated glioma cells (ionizing radiation) were able to modulate MMP2 activity in recipient cells, not by direct transfer but by regulating the expression of the corresponding gene." (PMID 29261132, 2017). "Furthermore, MALAT1-mediated tumor suppression in glioma cells may be via reduction of extracellular signal-regulated kinase/mitogen-activated protein kinase (ERK/MAPK) signaling activity and expression of matrix metalloproteinase 2 (MMP2)." (PMID 26938295, 2016). "Since it was not clear whether the membrane protein, particularly MMP-2, on the glioma cell surface bound by CTX could enter the cells by endocytosis, in order to prepare the CTX-Onc conjugate, a reversible chemical crosslinking approach was established." (PMID 25663909, 2015). "Matrix metalloprotease MMP-2—While searching for the molecular identity of the cell surface receptor of CTX, a 6His-tagged CTX analogue was designed and used to prepare an affinity column for mass spectrometry-mediated identification of CTX receptor from a solubilized human D54-MG glioma cell line." (PMID 25826056, 2015). "Several researches have indicated that CTX specifically binds to gliomas and tumors of neuroectodermal origin rather than non-neoplastic cells or normal brain, and this specific binding to cancer cells is facilitated by matrix metalloproteinase-2 (MMP-2)." (PMID 25128329, 2014). "The reduced expression of NCAM and PSA-NCAM may also be responsible for inhibiting migration of glioma cells independent of MMP-2 and 9 expressions, as there was no repopulation in scratched area in TCE treated cultures." (PMID 24205314, 2013). "Thus suggesting that the decrease in TEER of theRBMEC/ReNcells CX co-culture obtained after incubation with glioma C6 CM is not due to MMP-2 andMMP-9." (PMID 23637756, 2013). "This interaction stabilized FOXM1 protein levels and sequentially induced the expression of a series of oncogenes, such as MMP-2, VEGF, Chk2 and cyclin D1, which suggests that in addition to metabolic functions, PHGDH may have other biological roles in glioma tumorigenesis." (PMID 23229761, 2013). "The overlapping substrate panels of MT-MMPs, e.g., MMPs15, -16, and -24 are pro-MMP2 activators, suggest that these too might enhance the migration and infiltration of glioma cells; indeed, MMP15 and MMP16 have been demonstrated to enhance glioma cell migration in vitro." (PMID 32872536, 2020).
glioma (continued). "Interestingly, it was previously reported in gliomas that JNK may function as a positive regulator of MMP2 activity, not by interfering with the MMP expression but by the regulation of TIMP2 expression, an activator of the pro-MMP2." (PMID 25596741, 2015). "One of the main MMP2 functions is ECM remodeling leading to cell invasion, namely in gliomas, and since our group has previously demonstrated that WNK2 is a negative regulator of glioma cell invasion, it was further determined whether MMP2 is involved in invasion of WNK2-negative cells." (PMID 25596741, 2015). "MMP2 and, to a lesser extent, MMP9 were predictive of response, PFS, and OS in two independent small cohorts of patients with recurrent high-grade gliomas treated with bevacizumab, but not in a third cohort of patients treated by chemotherapy only." (PMID 34980260, 2022). "In addition, the secretion and activity of matrix metalloproteinases 2/9 (MMP‐2/‐9) were significantly suppressed in T98G cells treated with gartanin, and it might result from modulating mitogen‐activated protein kinases (MAPK) signalling pathway in T98G glioma cells." (PMID 27491646, 2017). "The results revealed support for significant publication bias in MMP-2 group (t = 3.90, P = 0.001) while did not reveal any publication bias among studies on TIMP-2 expression and glioma grade (t = −0.69, P = 0.521)." (PMID 26729052, 2017). "The 72 kDa protein reacted with anti-MMP2 antibody corresponding to proMMP-2 was observed in PANC-1 and glioma cells (A172) but not in SKBR-3 cells (used as a no/low-expressing control)." (PMID 24511528, 2014). "It has been widely documented that vessel co-option is a VEGF-independent mechanism of tumor vascularization, mainly driven by the proangiogenic factor ANG-2 without an increase in VEGF expression, and activation of matrix metalloproteinase-2 (MMP-2), which promotes glioma cell invasion." (PMID 36294763, 2022). "BmKCT interacts specifically with human glioma (SHG-44) cells, but not with normal astrocytes, as a Cl‒ channel blocker and inhibits the invasion and migration of rat glioma (C6) cells by antagonizing MMP-2." (PMID 30873475, 2017). "However, MMP-2 was constitutively expressed in glioma cells and PMA did not alter the expression level of MMP-2 or C2 ceramide treatments." (PMID 27043542, 2016). "MMP2, not as precise as HMGA2, could still auxiliarily indicate glioma poor prognosis." (PMID 29733521, 2018).